DCHS1 (dachsous cadherin-related 1)
Description:
Calcium-dependent cell-adhesion protein. Mediates functions in neuroprogenitor cell proliferation and differentiation. In the heart, has a critical role for proper morphogenesis of the mitral valve, acting in the regulation of cell migration involved in valve formation.
Synonyms: CDH25; FIB1; KIAA1773; PCDH16; FLJ11790; CDHR6; MMVP2; MVP2; VMLDS1
Tractability: Antibody: UniProt places it where antibodies can reach, with medium confidence; UniProt predicts a signal peptide or a membrane-spanning region; its Gene Ontology location is reachable by antibodies, with medium confidence; the Human Protein Atlas places it where antibodies can reach. PROTAC: its protein half-life has been measured.
Gene: Protein-coding gene on chromosome 11 (6,621,330 to 6,655,809, reverse strand). Ensembl gene ENSG00000166341.
Subcellular location: Cell membrane
Subcellular location (Human Protein Atlas): Plasma membrane
Gene Ontology:
Molecular function: beta-catenin binding; cadherin binding; calcium ion binding
Biological process: cell migration involved in endocardial cushion formation; mitral valve formation; calcium-dependent cell-cell adhesion; cell migration; cell-cell adhesion; heterophilic cell-cell adhesion; hippo signaling; neurogenesis; anatomical structure morphogenesis; cell adhesion; heart morphogenesis; homophilic cell-cell adhesion; mitral valve morphogenesis; tissue morphogenesis
Cellular component: catenin complex; membrane; apical part of cell; plasma membrane
Genetic constraint (gnomAD): Loss-of-function variants: 78 observed, 191.78 expected, observed/expected ratio (o/e) 0.41, 90% interval 0.34 to 0.49. The upper end of that interval is the gene's LOEUF score, 0.49, which puts it in group 2 of 6, group 1 being the genes least tolerant of losing a copy. Missense variants: 3,946 observed, 4,225.5 expected, observed/expected ratio (o/e) 0.93, 90% interval 0.91 to 0.96. Synonymous variants: 1,828 observed, 1,789 expected, observed/expected ratio (o/e) 1.02, 90% interval 0.98 to 1.06.
Gene-disease validity (ClinGen):
ClinGen rates the evidence that DCHS1 causes each of these diseases.
van Maldergem syndrome (autosomal recessive): Moderate.
congenital heart disease (autosomal dominant): Disputed. A heart disease that is present at birth.
Homologues: Orthologues: chimpanzee DCHS1 (99% identical), macaque DCHS1 (96% identical), rabbit DCHS1 (94% identical), guinea pig DCHS1 (94% identical), pig DCHS1 (93% identical), mouse Dchs1 (93% identical), rat Dchs1 (92% identical). Paralogues in human: DCHS2 (36% identical), CDH23 (25% identical), PCDH7 (8% identical), PCDH1 (8% identical), CDHR2 (8% identical), PCDH11X (7% identical), CDH1 (7% identical), PCDH9 (7% identical), PCDH11Y (7% identical), CDH3 (6% identical), CDH2 (6% identical), CDH4 (6% identical), and 21 more.
Diseases named in the same sentence as DCHS1 in open-access papers:
DCHS1 is named in the same sentence as 35 diseases in open-access papers, as found by Europe PMC text mining. Sharing a sentence is not in itself a finding about the gene and the disease. The quoted sentences say what the papers report.
van Maldergem syndrome (13 papers, 2015 to 2026). "Van Maldergem Syndrome (VMS) is a rare autosomal recessive disorder caused by pathogenic variants in the atypical cadherin genes DCHS1 or FAT4 and is marked by craniofacial, skeletal, and neurodevelopmental abnormalities." (PMID 41972678, 2026). "Fat4 and Dchs1 loss of function in mouse NSCs induced phenotypes resembling Van Maldergem syndrome with the formation of periventricular heterotopias." (PMID 32170161, 2020). "FAT4 and DCHS1 are directly implicated in the cause of Van Maldergem syndrome, a developmental disorder characterized by PH and function upstream of MOB2 in the Hippo signaling pathway." (PMID 29593499, 2018). "WES revealed compound heterozygous variants in DCHS1 (rs145099391:G > A, p.P197L & rs753548138:G > A, p.T2334 M) [RefSeq NM_003737.3], diagnostic of Van Maldergem syndrome (VMS-1)." (PMID 29046692, 2017). "Similarly, FAT4 and DCHS1 mutations in Hennekam syndrome and Van Maldergem syndrome patients, two genetic diseases that involve developmental defects in cell migration, are believed to cause a loss of function." (PMID 39478125, 2024). "We finally selected Dchs1 because of its relatively recent identification as a novel gene controlling the proliferation of neural progenitors and whose mutations is cause of developmental malformations, including heterotopia, in Van Maldergem syndrome." (PMID 30814272, 2019). "Mutations in the receptor-ligand cadherin pair DCHS1 (Dachsous cadherin-related 1) and FAT4 (FAT Atypical Cadherin 4) have been associated with the Van Maldergem syndrome, which is characterized by a periventricular neuronal heterotopia." (PMID 35069108, 2021). "Recent studies have demonstrated that mutations in the protocadherin genes DCHS1 and FAT4 are associated with Van Maldergem Syndrome." (PMID 33330619, 2020). "Fat4 and Dchs1 are receptor and ligand of the Hippo pathway, and mutations in FAT4 and DCHS1 cause Van Maldergem syndrome in humans." (PMID 32170161, 2020). "Interestingly, the inheritable brain dysplasia Van Maldergem syndrome (VMS; MIM601390) results from mutations of the Hippo upstream regulators Dchs1 and Fat4, and the phenotype in relevant mouse models can be rescued by YAP inhibition." (PMID 27935819, 2017).
mitral valve prolapse (9 papers, 2017 to 2025). A fairly common and often benign valvular heart disorder characterized by redundancy or hooding of mitral valve leaflets so that they prolapse into the left atrium, often causing mitral regurgitation. "Dachsous1 (Dchs1), an atypical cadherin linked to mitral valve prolapse, is a core planar cell polarity protein whose function in the developing heart has not been fully elucidated." (PMID 40497950, 2025). "For example, mutations in Dachsous cadherin-related 1 (DCHS1), the gene that codes for an atypical cadherin protein, have been identified in families with non-syndromic mitral valve prolapse." (PMID 38667724, 2024). "A recent study revealed that mutations in DCHS1 gene cause mitral valve prolapse with elongation, which suggests that MV specific gene might directly affect mitral leaflet enlargement even in HCM." (PMID 31660989, 2019). "DCHS1-HA was prominently expressed in the developing atrioventricular (AV) cushions and mitral valve tissue at all developmental stages examined, consistent with previous studies linking Dchs1 mutations to congenital mitral valve disease, including mitral valve prolapse and annular disjunction." (PMID 40497950, 2025). "Of these loci, the MMVP2 locus mutation was identified as a mutation in the DCHS1 gene, and the X-linked form of mitral valve prolapse mapped to Xq28 was identified as a mutation in the FLNA gene." (PMID 33671724, 2021).
Intellectual disability (3 papers, 2016 to 2025). "In particular, mutations in the gene encoding SYN1, that we found upregulated in both FAT4 and DCHS1 mutant and KO neurons and hCOs, have been associated with intellectual disability and epilepsy." (PMID 39966398, 2025).
endometrial carcinoma (2 papers, 2024 to 2025). A malignant tumor arising from the epithelium that lines the cavity of the uterine body. "Then we conducted some experiments to verify the function of DCHS1 in endometrial cancer in vitro." (PMID 39123216, 2024).
glioma (2 papers, 2024). A benign or malignant brain and spinal cord tumor that arises from glial cells (astrocytes, oligodendrocytes, ependymal cells). "DCHS1 (dachsous cadherin-related 1) may belong to some canonical cancer molecular pathways in gliomas and has been selected as a marker gene in glioma prognostic signature." (PMID 38474320, 2024).
Hennekam syndrome (2 papers, 2022 to 2024). Hennekam syndrome is characterized by the association of lymphoedema, intestinal lymphangiectasia, intellectual deficit and facial dysmorphism. "Mutations in Fat4 and DCHS1 are associated with Van Maldergem and Hennekam syndrome and many cancers." (PMID 35372364, 2022). "Mutations in FAT4 and DCHS1 are associated with many cancers and multi system developmental defects such as Van Maldergem syndrome and Hennekam syndrome, characterized by craniofacial anomalies, intellectual dysfunction, digital contractures, hypoplastic kidneys, sternal and auditory defects." (PMID 35372364, 2022).
Burkitt lymphoma (1 paper, 2021). A rare form of malignant mature B-cell non-Hodgkin lymphoma. "For Family 3 (Burkitt’s lymphoma), TNNT3, SIRPB1, TRMT1, ITGB4, and DCHS1 were the top-five ranked genes." (PMID 34624066, 2021).
choriocarcinoma (1 paper, 2023). An aggressive malignant tumor arising from trophoblastic cells. "DCHS1 was also proposed as a tumor suppressor gene candidate in gestational and non-gestational choriocarcinomas, and was found to be downregulated in colorectal tumors." (PMID 37296610, 2023).
chronic renal failure (1 paper, 2021). "In this study, we report a case of MVP with chronic renal failure with a heterozygous DCHS1 mutation." (PMID 33225636, 2021). "Therefore, we speculate that the DCHS1 mutations, promote podocyte apoptosis and enhance renal tubular cell autophagy, leading to chronic renal failure." (PMID 33225636, 2021). "The causal relationship between DCHS1 mutation and chronic renal failure has not yet been elucidated." (PMID 33225636, 2021).
developmental delay (1 paper, 2024). "In patient 5, a VUS (homozygous missense variant) in the DCHS1 gene was found, of which the patient matched the developmental delay and hearing problems associated with the gene, but not the pronounced dysmorphisms." (PMID 37889289, 2024).
familial mitral valve prolapse (1 paper, 2025). An instance of mitral valve prolapse (disease) that is caused by an inherited modification of the individual's genome. "The DCHS1 gene has been associated with familial mitral valve prolapse (MVP)." (PMID 39940965, 2025).
microtia (1 paper, 2019). "Of these, DCHS1 was strongly suggested to cause severe microtia-atresia as it was identified by both low-frequency and common variants association studies." (PMID 30691450, 2019). "Both low-frequency and common-variants association studies strongly suggested that DCHS1 was a cause of microtia-atresia." (PMID 30691450, 2019). "We identified several genes especially DCHS1 that strongly be associated with microtia-atresia through low-frequency or common variants association study." (PMID 30691450, 2019). "Using a Bonferroni-corrected significance level of 4.95 × 10− 5, two variants were identified that were significantly more common in our microtia-atresia patients: rs12288387 in DCHS1 (dachsous cadherin-related 1) and rs144123706 in GBA (glucosylceramidase beta)." (PMID 30691450, 2019).
Obesity (1 paper, 2021). Accumulation of substantial excess body fat. "To test these hypotheses in an independent cohort, we interrogated very rare variants (MAF < 0.025%) in TAOK2, DCHS1, and FAT4 in approximately 50,000 exomes from UK Biobank using a case–control approach for severe obesity (n = 925 cases, BMI > 40 kg/m2; n = 46,673 controls, BMI ≤ 40 kg/m2)." (PMID 34748544, 2021).
subependymal nodular heterotopia (1 paper, 2022). "Subependymal nodular heterotopias have been described in patients with chromosomal rearrangements, as well as associated with intragenic gene mutations (e.g., in FLNA, ARFGEF2, DCHS1, FAT4, ERMARD, and NEDD4L)." (PMID 35585091, 2022).
cancer (9 papers, 2021 to 2024). A tumor composed of atypical neoplastic, often pleomorphic cells that invade other tissues. "We further analyzed the association between DCHS1 expression and various immune infiltrates in human cancers by using TIMER2.0." (PMID 39123216, 2024). "We also performed GSEA pathway enrichment analysis and found that DCHS1 is associated with the EMT in various cancers." (PMID 39123216, 2024). "Our results displayed that DCHS1 expression was positively correlated with the immune infiltration of cancer associated fibroblast (CAF), Endothelial cell (EC), and Hematopoietic stem cell in most cancers." (PMID 39123216, 2024). "DCHS1 is differentially expressed in many cancers and its expression is significantly associated with tumor prognosis and diagnosis." (PMID 39123216, 2024). "Therefore, we conducted the expression, the prognostic, the diagnostic and epigenetic changes of DCHS1 in pan-cancer." (PMID 39123216, 2024). "DCHS1 expression was significantly correlated with the infiltration of cancer-associated fibroblasts (CAFs), Endothelial cell (ECs), and Hematopoietic stem cell in most cancers." (PMID 39123216, 2024). "We found that DCHS1 expression is positively associated with CAFs and ECs in pan cancers." (PMID 39123216, 2024). "ROC diagnostic curve indicated that DCHS1 might serve as a novel cancer biomarker for diagnostic application, especially in CESC, OV, UCEC, LUAD, LUSC, THYM." (PMID 39123216, 2024). "Based on the whole-exome sequencing of papillary thyriod microcarcinomas, researchers found that nonsynonymous mutations of 13 cell adhesion-related genes, including DCHS1, were only observed in the aggressive group, but the function of DCHS1 in pan-cancer was limited." (PMID 39123216, 2024). "Additionally, nearly all cancer-associated Fat4 and Dchs1 mutations in the COSMIC database are located outside of the binding interface, suggesting that the tumor suppressor role of Fat and Dachsous may not require their direct interactions." (PMID 36797229, 2023). "Meanwhile, we employed the immunohistochemistry results from HPA database to confirm the intensity of DCHS1 immunohistochemical staining in cancers." (PMID 39123216, 2024). "Next, we further investigated the expression of DCHS1 in pan-cancer through the RNA-seq data of TCGA." (PMID 39123216, 2024). "To explore the genetic alteration of DCHS1 in pan-cancer, we used the GSCA database to analyze genetic alterations and DNA methylation." (PMID 39123216, 2024). "GSEA results showed that DCHS1 was related to epithelial-mesenchymal transition (EMT) in many cancers." (PMID 39123216, 2024). "In our study, we found that DCHS1 expression was dysregulated in many cancers based on the pan-cancer analysis of TCGA and GTEx databases." (PMID 39123216, 2024). "Here, we conducted a pan-cancer analysis to evaluate the roles of DCHS1 across multiple databases and identify its value in prognosis and diagnosis." (PMID 39123216, 2024). "We further employed GSEA to investigate the main biological process affected by DCHS1 in pan-cancer." (PMID 39123216, 2024). "The diagnostic values of DCHS1 gene expression with AUC values of 0.966 for CESC, 0.924 for OV, 0.980 for UCEC, 0.926 for LUAD, 0.945 for LUSC and 0.949 for THYM indicated high diagnostic values in these cancers." (PMID 39123216, 2024). "We speculated that the variation in DCHS1 expression across different cancer types might be the result of the combination of genetic changes and epigenetic modifications under heterogeneous TME." (PMID 39123216, 2024). "Taken together, our study revealed that DCHS1 was differentially expressed in pan cancer, and it may serve as a potential tumor prognostic and diagnostic biomarker." (PMID 39123216, 2024). "There is a lack of more detailed research on the biological function of DCHS1 in pan-cancer." (PMID 39123216, 2024). "It has been also reported that FAT4 and DCHS1 may regulate autophagy in cancer cell lines and in renal tubular epithelial cells." (PMID 37609821, 2023).
cancer (continued). "Furthermore, KM survival curves confirmed that DCHS1 might be a potential reliable biomarker in some cancers." (PMID 39123216, 2024). "Subsequently, we analyzed the relationship between DCHS1 expression and Lymphocyte, immunomodulator, immunostimulators, MHC molecules and chemokine receptors in pan-cancer." (PMID 39123216, 2024). "By using TIMER2.0, we analyzed the correlation between DCHS1 and LIX1L in human cancer and found that DCHS1 expression was significantly positively correlated with LIX1L in pan-cancer." (PMID 39123216, 2024). "In pan-cancer analysis, SHOX2 expression positive correlated with CDKN2C (R = 0.41), COL6A1 (R = 0.35), COL6A2 (R = 0.37), DCHS1 (R = 0.37), MAPK7 (R = 0.34), PRRX1 (R = 0.37), RAB23 (R = 0.36) and RSRC1 (R = 0.36) via GEPIA2." (PMID 37170390, 2023). "Furthermore, the expression of top 5 genes (DCHS1, PRKG1, TGFBR2, TNS1, and TTC28) in the majority of detailed cancer types was shown in the form of heatmap." (PMID 36051999, 2022). "Further studies would be needed to elucidate whether DCHS1 is involved in CAF-mediated cancer metastasis or not." (PMID 35216340, 2022). "In addition, primary cancer cells did not express DCHS1 and GLIS1 mRNA and protein." (PMID 35216340, 2022).
tumor (6 papers, 2010 to 2024). "We analyzed the correlation between DCHS1 expression and immune signature / tumor immune cell infiltration in the TCGA database by using UCSCXenaShiny online database." (PMID 39123216, 2024). "Firstly, in our work, we found the positive relationship between anti-tumor gene DCHS1 expression and CAFs and ECs." (PMID 39123216, 2024). "Concerning the expression of the markers in tumor-associated microglia/macrophages and in accordance with our findings, an expression of SKI, Cables1, and DCHS1 was also described by previous studies." (PMID 37296610, 2023). "Moreover, the association between DCHS1 expression and tumor mutation burden (TMB), microsatellite instability (MSI), stemness and drug sensitivity was examined to explore its value on tumor immunotherapy." (PMID 39123216, 2024). "In different tumor types, DCHS1 seems to execute a tumor-suppressive effect." (PMID 37296610, 2023). "In our study, CCRL1, SLFN13, SKI, Cables1, and DCHS1 were all shown to be regulated under TMZ-promoted dormancy and, besides tumor cells, to be expressed by endothelial cells and tumor-associated microglia/macrophages." (PMID 37296610, 2023). "The results indicated that AIFM3, HSH2D, and PTPN6 were significantly up-regulated, while DCHS1, PTGIS, FLRT2, PCSK5, and CLSTN2 were significantly down-regulated in tumor samples compared with normal samples." (PMID 34512722, 2021). "Some of these genes were upregulated in our analyses of skin KS (BTAF, VMP1, DCHS1, VCAM1, PLXND1)." (PMID 37740179, 2023).
DCHS1 also shares sentences with these, for which no sentence is quoted: Cognitive impairment (2 papers); calcification (1); Carpenter syndrome (1); channelopathies (1); colon adenocarcinoma (1); colorectal tumors (1); epithelial-myoepithelial carcinoma (1); Esophageal carcinoma (1); genetic diseases (1); heterotopia (1); hypogonadotropic hypogonadism (1); Marfan syndrome (1); Mitral regurgitation (1); musculoskeletal disorders (1); pituitary hormone deficiencies (1); pituitary stalk interruption syndrome (1); rectum adenocarcinoma (1); Robinow syndrome (1); salivary duct carcinoma (1).